INS (insulin)
Diseases named in the same sentence as INS in open-access papers (continued):
Sharing a sentence is not in itself a finding about the gene and the disease.
diabetes (continued). "The high average BMI and prevalence of non-insulin-dependent management methods in diabetes management highlight the significance of lifestyle interventions and weight management, consistent with previous studies." (PMID 38741878, 2024). "LCAT activity measured in the blood of diabetes patients before and after insulin treatment confirmed that glucose on its own cannot activate LCAT23." (PMID 39478139, 2024). "Impaired insulin action and secretion, glucose intolerance, and hyperglycemia are the major features of type 2 diabetes mellitus (T2DM), a metabolic disorder that accounts for 90% of diabetes cases." (PMID 39404390, 2024). "The pancreatic islets were particularly investigated to elucidate the role of RDR in ameliorating STZ-induced diabetes and its therapeutic impact on insulin secretion." (PMID 39201631, 2024). "There were 107 patients (62.9%) who consulted with a specialist in the Diabetes Endocrinology Department preoperatively and 118 (69.4%) who required sliding-scale insulin during the perioperative period." (PMID 38915109, 2024). "Regular aerobic exercise is a routine treatment option for addressing diabetes mellitus, and aerobic training can reduce glycated hemoglobin levels, increase maximal oxygen uptake, and improve insulin sensitivity in patients with T2DM." (PMID 38978627, 2024). "Diabetes is an inflammatory disease, and elevated blood glucose level and insulin insensitivity leads to the activation of immune cells, thereby secreting interleukins and cytokines such as IL-6 and TNF-α and aggravating the inflammatory response." (PMID 39144694, 2024). "Hypoglycemia during insulin infusion was seen in 55 patients (17.35%): 9 with diabetic ketoacidosis (20.03%), 45 with combined diabetic ketoacidosis-hyperosmolar state (42.02%), and 2 with hyperosmolar state (22.2%) (p < 0.04)." (PMID 39079150, 2024). "Diabetes mellitus is a chronic, multifaceted metabolic disease characterized by hyperglycemia or elevated blood glucose levels resulting from abnormalities in insulin secretion, insulin action, or both." (PMID 39104999, 2024). "Intermittently Scanned Continuous Glucose Monitoring (isCGM), also known as Flash Glucose Monitoring (FGM), is a well-known valuable tool for managing patients with diabetes undergoing insulin treatment, including those with Type 2 Diabetes Mellitus (T2DM)." (PMID 38337336, 2024). "Although MODY accounts for 1–4% of paediatric diabetes, misdiagnosis still results in many young people being treated unnecessarily with insulin." (PMID 38513803, 2024). "Diabetes mellitus (DM) is a persistent metabolic condition characterized by hyperglycemia due to inadequate insulin levels." (PMID 38586730, 2024). "An important mechanism linking obesity to diabetes is mitochondrial dysfunction, which leads to impairments in insulin sensitivity in target tissues and compromises pancreatic β-cell function." (PMID 38981607, 2024). "Diabetes is a multifaceted metabolic disorder characterized by chronic hyperglycemia stemming from defects in insulin secretion, insulin action, or both." (PMID 39685817, 2024). "Diabetes is a metabolic defect identified by hyperglycemia due to irregularities in the secretion and action of insulin." (PMID 39203772, 2024). "Our study found that STZ-induced diabetes leads to higher fasting blood glucose and lower serum insulin levels by destroying pancreatic islet cells through oxidative stress, metabolic disruption, and impaired mitochondrial function." (PMID 39391856, 2024). "Future research should further explore the underlying mechanisms and clinical implications of these findings, particularly for optimizing insulin therapy in diabetes management." (PMID 39386695, 2024). "Research has shown its potential in treating diabetes by regulating insulin secretion, improving glucose homeostasis, and acting as a cytoprotective antioxidant." (PMID 39062777, 2024).
diabetes (continued). "The prolonged elevation of insulin production and secretion during the pathogenesis of diabetes results in β-cell ER stress." (PMID 38927260, 2024). "It contains patient features such as pregnancies, plasma glucose levels measured through oral glucose tolerance test, blood pressure, skin thickness, serum insulin, BMI, age, and diabetes pedigree function." (PMID 39238969, 2024). "Defective autophagy in pancreatic beta cells has been shown to be involved in the progression of diabetes through impaired insulin secretion under glucolipotoxic stress." (PMID 38297165, 2024). "Diabetes mellitus (DM) is a chronic metabolic disorder characterized by persistent hyperglycemia, which results from defects in insulin secretion, insulin action, or both." (PMID 39483560, 2024). "Enhanced insulin sensitivity and reduced inflammation from regular exercise contribute to better physical health and reduced diabetes-related complications." (PMID 38999476, 2024). "Insulin is an anabolic hormone used clinically to reduce blood glucose levels in patients with diabetes by enhancing glucose uptake and metabolism in cells." (PMID 38374190, 2024). "The diabetes medications included metformin (n = 11), sulfonylurea (n = 6), insulin (n = 5), glucagon-like peptide 1 receptor agonists (GLP-1RA) (n = 4), and gliptins (n = 3)." (PMID 39381685, 2024). "His contribution was instrumental in discovering insulin, a practical and life-saving treatment for diabetes." (PMID 39691108, 2024). "Of note, in most cases, diabetes remitted within days to weeks after insulin was discontinued, but three cases were reported to remain insulin-treated as old as 41- 60 months of age at the time of the reports." (PMID 39025920, 2024). "Elicit the experiences and perspectives of older or frail adults with diabetes and HCPs in relation to insulin use in surgical care settings." (PMID 39666732, 2024). "Baseline characteristics—Medicare Advantage patients with diabetes by average insulin out of pocket cost per 30‐day supply." (PMID 36992575, 2024). "Diabetic ketoacidosis was reported in half of the cases, and diabetes mellitus was well controlled with insulin." (PMID 39420940, 2024). "They observed a rapid decline in demand for exogenous insulin in children with diabetes after regular insulin treatment." (PMID 38981114, 2024). "Regarding the results of the glycated hemoglobin, group A showed a reduction in HbA1c values, indicating that the educational intervention for insulin therapy in diabetes is effective for efficient glycemic control." (PMID 38541647, 2024). "The progression from obesity to diabetes mellitus is a continuum that spans various stages, wherein defects in insulin resistance and insulin secretion play a crucial role in their interaction." (PMID 38436759, 2024). "With regard to diabetes-related treatment, most diabetics were treated with insulin (38.0%), followed by metformin (36.7%)." (PMID 38337436, 2024). "MSC therapy is an innovative approach in diabetes due to its capacity to modulate the tissue microenvironment and regenerate glucose-responsive insulin-producing cells." (PMID 38455849, 2024). "Diabetes technology use was high, with 79% using insulin pumps (68% hybrid-closed loop) and 93% using continuous glucose monitors (CGM)." (PMID 38774897, 2024). "Insulin is a protein hormone commonly used for the treatment of diabetes, which is secreted by islet cells to regulate blood glucose." (PMID 38167129, 2024). "Approximately 90 % of all diabetes cases are type 2 diabetes mellitus (T2DM), which is a multifactorial disease characterized by persistent hyperglycemia caused by pancreatic β-cell dysfunction and abnormal insulin action and secretion." (PMID 38333854, 2024). "In both sexes, MISATP was correlated with obesity (waist circumference), insulin resistance (HOMA-IR, triglycerides), and diabetes (HbA1c, fasting blood glucose, insulin)." (PMID 39453155, 2024).
diabetes (continued). "KD is shown to have a beneficial effect in patients with type 2 diabetes by reducing oral intake along with concordant reductions in insulin requirements and the amount of other anti-diabetes therapies." (PMID 39328462, 2024). "A high degree of suspicion is warranted in toddlers, teenagers (with a known history of diabetes) and patients with an insulin pump." (PMID 39099754, 2024). "Based on our findings, SDOs can reduce the deterioration effect of diabetes through a variety of mechanisms, including stimulating insulin secretion from beta cells, aiding in beta-cell recovery, and increasing the number of beta cells." (PMID 39063270, 2024). "Defects in insulin secretion can lead to diabetes mellitus, characterized by persistent hyperglycemia along with severe complications." (PMID 39125265, 2024). "The use of diabetes technology in older adults is discussed in the following sections; under the umbrella term ‘diabetes technology’ we have included connected insulin pens, CGM, insulin pumps and automated insulin delivery (AID) systems." (PMID 39138689, 2024). "Diabetes is a life-threatening disease that arises due to the insufficient production of insulin by the pancreas (type 1 diabetes) or the human body's failure to properly use produced insulin (type 2)." (PMID 38515931, 2024). "Patients can choose to read by themselves or ask diabetes educator or staff nurse to help them to go through the insulin PDA with them prior to their consultation with doctors." (PMID 39546450, 2024). "This suggests that nano-curcumin enhances insulin sensitivity and glucose transport, crucial for diabetes management." (PMID 39759349, 2024). "Dawn phenomenon refers to a spontaneous hyperglycemia or an increased demand for insulin to maintain normoglycemia in the early morning, which affects nearly half of the diabetes patient population." (PMID 38584275, 2024). "BCAA, and potentially toxic metabolites such as BCAA-derived acylcarnitines, can however directly or indirectly interfere with insulin action and contribute to the development of insulin resistance and diabetes." (PMID 39114126, 2024). "Increased BMI and obesity increased insulin sensitivity, made weight control difficult, and worsened diabetes control." (PMID 39121323, 2024). "MODY13 is an autosomal dominant form of diabetes caused by mutations in the KCNJ11 gene, and the pathological basis is the dysfunction of pancreatic beta cells and absolute deficiency of insulin secretion." (PMID 38095268, 2024). "Type 1 diabetes mellitus generally occurs when the immune system erroneously attacks and destroys the insulin-producing β-cells in the pancreas, significantly reducing or completely halting insulin production." (PMID 39777222, 2024). "A prolonged duration of diabetes and the administration of insulin are indicative of more advanced cases, leading to a relatively higher prevalence of DSPN in these diabetic patients." (PMID 38959204, 2024). "Conversely, the highest glucose levels observed in the ZOD rats, along with lower insulin levels compared with the ZO rats, indicate fully developed diabetes, corroborating earlier observations." (PMID 39452068, 2024). "We describe a case of a 43-year-old woman with type 1 diabetes mellitus (DM), severe insulin resistance, and subcutaneous nodules at injection sites, accompanied by elevated anti-insulin IgG autoantibodies." (PMID 38469413, 2024). "The management of T1D primarily involves intensive insulin regimens, which consist of multiple daily injections or, given the recent advancements in diabetes technology, insulin pump therapy." (PMID 39334618, 2024). "GDM, diabetes that develops during pregnancy, is a state of heightened insulin resistance, insufficient pancreatic insulin production, hyperglycemia, immune dysregulation, and altered vaginal microbial composition." (PMID 39033123, 2024).
diabetes (continued). "Therefore, the recent American Diabetes Association (ADA) guidelines have suggested that isCGM should be offered for diabetes management in patients with type 2 diabetes on multiple daily injections or continuous subcutaneous insulin infusion who are capable of using the devices safely." (PMID 38337336, 2024). "As we all know, diabetes is a chronic metabolic disease that occurs when the body cannot effectively use or produce insulin." (PMID 39272484, 2024). "This association needs to be further investigated to understand in depth its role in mediating the effect of GALNT2 on insulin sensitivity, glucose control and other clinical features in people with diabetes." (PMID 38627282, 2024). "Six months after the initial intervention, 45.2% of patients following IST and 45.9% of patients following IET had diabetes mellitus, either insulin-dependent or on oral medication (p = 0.946)." (PMID 38347181, 2024). "Thisprocess is dysregulated in diabetes, and many questions remain onhow the cell controls insulin maturation." (PMID 39504473, 2024). "Recombinant insulin is a life-saving therapeutic for millions of patients affected by diabetes mellitus." (PMID 38703998, 2024). "Elevated glucose levels in the blood due to insulin secretion defects characterize diabetes mellitus, a metabolic disorder." (PMID 38474670, 2024). "Compared with the diabetes group, fasting insulin was significantly decreased in all three P. copri treatment groups (P < 0.05)." (PMID 38934548, 2024). "First, parents had the perception that their children would benefit by participation in the study, since they would have access to advanced technology as insulin pump and sensors already from the first week after diabetes diagnosis." (PMID 39360673, 2024). "It is becoming increasingly indicated that patients with insulin-depending diabetes use CGM systems nowadays." (PMID 38572446, 2024). "Being overweight is a relevant contributor to the development and progression of type 2 diabetes mellitus (T2 DM) and leads to decreased insulin response and subsequently to diminished pancreatic insulin secretion later in the course of the disease." (PMID 39274338, 2024). "Alterations in lipid homeostasis in live and insulin sensitive tissues – are pivotal in the onset of decreased insulin sensitivity, impaired glucose absorption, hyperglycemia and type 2 diabetes mellitus (T2D)." (PMID 38755663, 2024). "Faecalitalea belonging to the phylum Firmicutes can ferment d-glucose, sucrose, d-mannose, and raffinose; the main end product of metabolism is butyric acid, which promotes postprandial insulin secretion and improves insulin response in patients with diabetes." (PMID 39196875, 2024). "Diabetes is a metabolic disorder in which the body produces less INS or has reduced sensitivity to INS." (PMID 38313028, 2024). "Mean diabetes duration was 14.2 ± 10.7 years, mean HbA1c 7.4 ± 3.0% (56.9 ± 9.1 mmol/mol), mean BMI 31.0 ± 5.2 kg/m2, and 59% (35 persons) used insulin, of which 71% (25 people) were on a multiple daily injection regimen." (PMID 39458552, 2024). "GLUT-4 is a key mediator of insulin-stimulated glucose uptake in skeletal muscle, and its reduction is indicative of the profound impact of impaired muscle glucose uptake in diabetes." (PMID 39684905, 2024). "Adequate dietary protein not only helps maintain muscle mass but also promotes body fat regulation and has positive effects on insulin sensitivity and blood glucose control, aiding in diabetes management." (PMID 38612998, 2024). "By identifying specific fears and misconceptions, healthcare providers can use ITAS to create more personalized diabetes management plans and overcome barriers in the timely initiation of insulin treatment." (PMID 39453515, 2024). "Overexpression of MYC in cellular and animal models has led to increased beta cell proliferation, apoptosis and down-regulation of insulin gene leading to diabetes." (PMID 39464889, 2024).
diabetes (continued). "A substantial body of evidence from numerous studies indicates that osteocalcin plays a role in regulating insulin secretion and in the prevention and treatment of diabetes." (PMID 39872315, 2024). "While only a few patients had uncontrolled diabetes (16.67% and 20%, respectively), requiring initiation of insulin therapy, glycemic control was achieved in three to four days." (PMID 39744274, 2024). "Specific keywords related to medicinal plants, herbal medicine, phytotherapy, traditional medicine, Psidium guajava, Seriphium plumosum L., diabetes, hyperglycemia, glucose metabolism, and insulin resistance were used to retrieve relevant articles." (PMID 38931040, 2024). "The three main SCFAs are butyrate, propionate, and acetate, and in many studies, they are suggested to have an impact on glucose metabolism and insulin sensitivity, thereby affecting the development of diabetes." (PMID 38931292, 2024). "α-cells, especially those secreting glucagon, have the capacity to spontaneously transform into insulin-producing cells, thereby aiding in diabetes recovery, particularly post-puberty." (PMID 39057094, 2024). "Diabetes had been present for a mean of 20.6 ± 10.7 years and was treated by insulin in 76% of the cases." (PMID 39858984, 2024). "Currently, insulin is also being researched for its neuroprotective effect after intranasal administration, in addition to its use in the treatment of diabetes." (PMID 39408782, 2024). "High glucose levels can lead to hypoglycaemia due to correction of elevated glucose in insulin‐treated individuals with diabetes." (PMID 39632776, 2024). "Diabetes-induced cognitive dysfunction involves multiple mechanisms, such as abnormal insulin signaling, amyloid-β accumulation, oxidative stress, and inflammation." (PMID 39822457, 2024). "Chemically induced experimental models are frequently chosen to test new diabetes medications and insulin formulations." (PMID 38837635, 2024). "The main drugs used to treat diabetes include biguanides, sulfonylureas, glinides, glucosidase inhibitors, thiazolidinediones, and insulin analogues." (PMID 39028269, 2024). "It is important to note that the majority of children with T1DM are using diabetes technologies, such as insulin pumps (continuous subcutaneous insulin infusion, CSII), CGMs, or hybrid closed-loop systems (artificial pancreas)." (PMID 39408305, 2024). "In one case of pre-existing severe type 2 diabetes mellitus, nilotinib was shown to directly affect glucose metabolism via impairment of endogenous insulin secretion." (PMID 38362147, 2024). "Diabetes mellitus (DM) is a group of metabolic disorders characterized by elevated levels of glucose in the blood resulting from defects in insulin secretion, insulin action, or both." (PMID 39086905, 2024). "This action is pivotal in rectifying insulin signaling pathways and mitigating the effects of diabetes." (PMID 39633648, 2024). "Diabetes mellitus is a heterogeneous group of metabolic and health conditions characterized by glucose dysregulation and defects in insulin secretion and/or insulin action." (PMID 38890458, 2024). "Type 1 diabetes mellitus (T1D) is an autoimmune-related disease resulting in insulin dependency, treated with insulin injection via pen devices or continuous subcutaneous insulin infusion (CSII)." (PMID 38313889, 2024). "A Japanese study found that the dosage of insulin used by patients with diabetes and HD was not only reduced, but also the incidence of asymptomatic hypoglycemia on HD day was reduced from 38.1% to 19.0%." (PMID 39628691, 2024). "Despite well-controlled T2DM with oral hypoglycemic agents, the initiation of immune checkpoint inhibitors (ICIs) led to rapid deterioration into insulin-dependent status due to ICI-induced type 1 diabetes mellitus (T1DM)." (PMID 38681275, 2024).